IGLJ1 (immunoglobulin lambda joining 1)
Description:
J region of the variable domain of immunoglobulin lambda light chains that participates in the antigen recognition. Immunoglobulins, also known as antibodies, are membrane-bound or secreted glycoproteins produced by B lymphocytes. In the recognition phase of humoral immunity, the membrane-bound immunoglobulins serve as receptors which, upon binding of a specific antigen, trigger the clonal expansion and differentiation of B lymphocytes into immunoglobulins-secreting plasma cells. Secreted immunoglobulins mediate the effector phase of humoral immunity, which results in the elimination of bound antigens. The antigen binding site is formed by the variable domain of one heavy chain, together with that of its associated light chain. Thus, each immunoglobulin has two antigen binding sites with remarkable affinity for a particular antigen. The variable domains are assembled by a process called V-(D)-J rearrangement and can then be subjected to somatic hypermutations which, after exposure to antigen and selection, allow affinity maturation for a particular antigen.
Gene: Immunoglobulin joining (J) gene on chromosome 22 (22,893,692 to 22,893,818, forward strand). Ensembl gene ENSG00000211674.
Subcellular location: Secreted; Cell membrane
Gene Ontology:
Cellular component: extracellular region; plasma membrane
Genetic constraint (gnomAD): Missense variants: 54 observed, 46.67 expected, observed/expected ratio (o/e) 1.16, 90% interval 0.93 to 1.45. Synonymous variants: 24 observed, 19.97 expected, observed/expected ratio (o/e) 1.2, 90% interval 0.87 to 1.68.